CHIA (chitinase acidic)
Diseases named in the same sentence as CHIA in open-access papers:
CHIA is named in the same sentence as 53 diseases in open-access papers, as found by Europe PMC text mining. Sharing a sentence is not in itself a finding about the gene and the disease. The quoted sentences say what the papers report.
asthma (41 papers, 2007 to 2025). "Previous studies have indicated that chitinase 3-like 1 (CHI3L1) gene rs4950928 polymorphism and acidic mammalian chitinase (AMCase or CHIA) gene rs10494132 polymorphism are associated with the risk of asthma." (PMID 29233108, 2017). "When population was stratified based on ethnicity, a positive correlation between CHIA rs10494132 polymorphism and asthma risk was found in Asians." (PMID 29233108, 2017). "Recent genetic study has described that several CHIA polymorphisms is related to asthma risk in a German pediatric population." (PMID 29233108, 2017). "The large SVs also contained genes related to immune response, such as LY9, ITLN2, and CHIA, which may be linked to asthma susceptibility in the JH pig." (PMID 40372724, 2025). "The ITLN2 and CHIA genes have been reported to link to asthma susceptibility in humans." (PMID 40372724, 2025). "Firstly, sample size in this meta-analysis was small, which might result in bias of the results when evaluating the association of CHI3L1 and CHIA gene polymorphisms with susceptibility to asthma." (PMID 29233108, 2017). "Moreover, in the subgroup analysis conducted according to age, CHIA rs10494132 variant was also found to be associated with the increased risk of asthma in children." (PMID 29233108, 2017). "After a systematical literature search based on the inclusion criteria, 10 case-control studies from 8 published articles containing 1858 cases and 1778 controls were identified for this meta-analysis to investigate the relations of CHI3L1 and CHIA variants with asthma risk." (PMID 29233108, 2017). "Therefore, it is important to perform a meta-analysis of all eligible studies to clarify the effects of CHI3L1 rs4950928 polymorphism and CHIA rs10494132 variant on risk of asthma." (PMID 29233108, 2017). "Furthermore, subgroup analysis by ethnicity revealed a positive correlation between CHIA rs10494132 polymorphism and asthma risk among Asians (TT vs. TC + CC: OR = 1.476, 95% CI = 1.071–2.032, P = 0.017; T vs. C: OR = 1.326, 95% CI = 1.024–1.717, P = 0.032)." (PMID 29233108, 2017). "Furthermore, the CHIA enzyme has been found to be a downstream protein of interleukin-13, a cytokine implicated in the effect of human asthma." (PMID 29233108, 2017). "Therefore, a systematic meta-analysis was important to clarify the effect of CHI3L1 rs4950928 polymorphism and CHIA rs10494132 variant on asthma risk." (PMID 29233108, 2017). "Additionally, in the subgroup analysis conducted according to age, CHIA rs10494132 variant was also found to be associated with the increased risk of asthma in children (TT vs. TC + CC: OR = 1.472, 95% CI = 1.067–2.030, P = 0.019; T vs. C: OR = 1.320, 95% CI = 1.016–1.713, P = 0.037)." (PMID 29233108, 2017). "For example, CHIA expression is upregulated during allergic airway responses in mouse models of asthma." (PMID 35056724, 2022). "Study has observed that serum CHIA level is overexpressed in ovalbumin-induced mouse model of asthma." (PMID 29233108, 2017). "However, the rs10494132 polymorphism of CHIA might be a risk factor for asthma." (PMID 29233108, 2017). "CHIA is involved in the pathogenesis of asthma and pulmonary fibrosis." (PMID 35056724, 2022). "Therefore, the CHIA enzyme has been suggested to be a positive mediator involved in the pathogenesis of asthma." (PMID 29233108, 2017). "Secondly, Using RP, we report for the first time an interaction of six genes affecting European ancestry pediatric asthma: rs2243250 (IL4), rs6597 (STUB1) rs11168070 (ADRβ2), rs3024676 (IL4Rα), rs638376 (IL13Rα2) and rs3806446 (CHIA)." (PMID 21387019, 2011). "In addition, inhibition of CHIA expression reduced TH2-dependent airway inflammation, bronchial hyper-reactivity, and eosinophil counts in these asthma mouse model." (PMID 29233108, 2017).
asthma (continued). "Chitinases, chitotriosidase (CHIT1), acidic mammalian chitinase (AMCase or CHIA), and nonenzymatic chitinase-3-like protein 1 (CHI3L1) have been implicated in various pathological conditions, such as Gaucher’s disease (CHIT1), obesity, diabetes, cardiovascular diseases, and asthma (CHIA)." (PMID 35330193, 2022).
viral infection (3 papers, 2013 to 2023). "The native viral expression and enzymatic regulation of both CHIA and V-CATH has evolved to result in an effective viral infection process." (PMID 36851718, 2023). "We previously determined that CHIA overexpression by Acp6.9-chiA did not compromise virus infection kinetics relative to AcEGFP and AcMNPV." (PMID 36851718, 2023).
colitis (2 papers, 2022 to 2024). Inflammation of the colon. "ChiA has been implicated in the virulence of some adherent/invasive E. coli strains that cause colitis." (PMID 39268542, 2024).
gastric atrophy (2 papers, 2022 to 2025). "Previously, it has been found that the upregulation of ITLN1 is associated with GC onset in humans, and that downregulation of CHIA causes gastric atrophy." (PMID 35426084, 2022). "The consistent downregulation of CHIA (acidic chitinase), a gene linked to mucosal immunity and gastric inflammation, is particularly notable given its association with Helicobacter pylori-related gastric atrophy and cancer." (PMID 40725485, 2025).
atopic asthma (1 paper, 2020). An asthma that is characterized by symptoms that are triggered by an allergic reaction caused by inhaled allergens such as dust mite allergen, pet dander, pollen and mold. "The authors identified three specific promoter polymorphisms associated with atopic asthma, total serum IgE, or both, confirming the role of CHIA as an asthma susceptibility gene." (PMID 33324573, 2020). "Another study investigated the role of acidic mammalian chitinase (CHIA) in atopic asthma, through detection of polymorphisms of this gene in asthmatic patients in Northern India." (PMID 33324573, 2020).
enteritis (1 paper, 2024). Inflammation of the small intestine. "Both an in vivo colonization trial and a necrotic enteritis trial were conducted, demonstrating that a ChiA chitinase mutant strain was less capable to colonize the intestine and was hampered in its disease-causing ability as compared to the wild-type strain." (PMID 39283899, 2024).
Legionnaires' disease (1 paper, 2020). A pneumonia caused by Legionella pneumophila and other Legionella species, which is characterized by fever, cough, progressive respiratory distress, and which is often accompanied by extrapulmonary manifestations. "Legionella pneumophila is the causative agent of Legionnaires' disease, an often-fatal pneumonia and its chitinase ChiA is essential for the survival of L. pneumophila in the lung." (PMID 32365117, 2020). "Legionella pneumophila causes Legionnaires’ disease, a severe form of pneumonia, and its chitinase ChiA is essential for the survival of L. pneumophila during infection of the lung." (PMID 32365117, 2020).
mastitis (1 paper, 2024). Inflammation of breast tissue during lactation or postpartum due to an obstructed duct or infection. "The type 2 secretion system and chiA were also more frequently associated with mastitis-causing strains than with commensals." (PMID 39268542, 2024).
neuroblastoma (1 paper, 2025). Neuroblastoma (NB) is the most common solid, extracranial childhood tumor. "Other notable genes include (i) NPBF3, part of the neuroblastoma breakpoint family; (ii) APOL5, from the apolipoprotein L gene family; (iii) CHIA, which plays a role in chitin degradation; and (iv) TTN, which encodes a prominent protein in striated muscle." (PMID 39774017, 2025).
prostate carcinoma (1 paper, 2020). A carcinoma that arises from epithelial cells of the prostate gland. "However, when we analyzed gene expressions in several human prostate cancer datasets, the identified groups with higher mRNA levels of the three genes (IL1RN, CD11B, and CHIA) did not overlap (mRNA High)." (PMID 33322099, 2020).
Salmonella Infections (1 paper, 2022). Infections with bacteria of the genus SALMONELLA. "We further showed that the absence of chiA failed to downregulate the surface MHC-II molecules on the activated macrophages, which is a well-known phenomenon during Salmonella infection." (PMID 35482710, 2022).
infection (18 papers, 2008 to 2024). The state of being infected such as from the introduction of a foreign agent such as serum, vaccine, antigenic substance or organism. "For example, in the important foodborne pathogen Listeria monocytogenes, the chitinases ChiA and ChiB and the lytic polysaccharide monooxygenase Lmo2467 are implicated in chitin assimilation but also act as virulence factors during the infection of mammalian hosts." (PMID 28887418, 2017). "Since only chiA, and not chiB, is targeted by LhrA, we speculate that LhrA-regulation could be linked to a ChiA-specific substrate in the external environment, or possibly during infection, which would require differential regulation of the two genes." (PMID 21533114, 2011). "Alternatively, it is possible that ChiA contributes to infection through glycosidase activity, independently of its binding to host proteins." (PMID 39268542, 2024). "The polh promoter enabled higher (4.5X) CHIA enzyme production (at 48 h post infection [p.i.]), but the p6.9 promoter resulted in earlier transcription of chiA and increased CHIA enzyme levels (1.5X) at 48 h p.i. in infected cells." (PMID 36851718, 2023). "Infection with the dual reprogrammed Acp6.9-chiA/polh-cath virus, in which chiA is expressed under the p6.9 promoter and v-cath under the polh promoter, led to earlier larval death and liquefaction relative to infection with AcEGFP, Acp6.9-chiA, or AcMNPV-Rep." (PMID 36851718, 2023). "The expression of chiA has been detected during infection of epithelial cells, murine macrophages, and the gastrointestinal system of chickens." (PMID 35482787, 2022). "Although Salmonella chiA was upregulated during infection, the role of this chitinase in Salmonella pathogenesis remains elusive." (PMID 35482710, 2022). "A functional role for S. Typhimurium chitinases during infection has been suggested based on the observations that chiA is upregulated during the infection of epithelial cells, murine macrophages, and the chicken gastrointestinal system." (PMID 35482787, 2022). "Our work provides novel molecular insight into the virulence mechanism of a bacterial chitinase and suggests that ChiA has a role in modulating host immune responses and facilitates L. pneumophila penetration of the alveolar mucosa during infection." (PMID 32365117, 2020). "This is the first mechanistic understanding of how a chitinase can promote disease through additional peptidase activity and suggests that L. pneumophila ChiA can modulate host immune responses and disperse host mucosa during infection." (PMID 32365117, 2020). "Rather, we posit that translocated ProA and ChiA are involved in the middle stages of intracellular infection and in further maturation of the LCV, processes that are relatively insufficiently studied in the Legionella field." (PMID 28634242, 2017). "Because ProA and ChiA gain access to the host cell cytoplasm, they likely have a broader role in intracellular infection than previously imagined." (PMID 28634242, 2017). "Intriguingly, despite the absence of chitin in human and mammalian hosts, both of the chitinases have been deemed important for infection, through a mechanism that, at least in the case of ChiA, involves modulation of host immune responses." (PMID 24752234, 2014). "The activity was more intense at 72 h p.i. which is consistent with previous studies that have shown the expression of CHIA late in infection." (PMID 24086357, 2013). "A. gemmatalis larvae inoculated with AgMNPV and vAgp2100Cf.chiA/v-cath were dissected and their internal organs were observed at different times post infection." (PMID 24086357, 2013). "The analysis of chiA and v-cath transcripts in insect cells infected with AcMNPV and vAgp2100Cf.chiA/v-cath by qRT-PCR showed the presence of both transcripts from early to late phases of infection." (PMID 24086357, 2013).
infection (continued). "Transcripts of v-cath and chiA genes were detected along the infection of insect cells by qRT-PCR, from early to late phases of infection." (PMID 24086357, 2013). "However, chiA expression was detected in infection models and purified ChiA cleaved carbohydrate subunits present on mammalian surface glycoproteins, indicating a role during pathogenesis." (PMID 35482787, 2022). "Some bacterial chitinases and chitin binding proteins are able to promote infection through adhesion to and/or degradation of host glycoconjugates and we hypothesized that ChiA may interact with exogenous mucins in the lungs and elsewhere." (PMID 32365117, 2020). "Since the regulatory pathway behind the induction of chiA during infection remains elusive, it would be of interest to examine whether it involves agr, especially as agr itself has previously been found to be important for pathogenicity." (PMID 24752234, 2014). "However, they are less able to survive in the lungs of A/J mice, suggesting that ChiA is required for optimal survival of L. pneumophila in the lungs, although how it is able to promote infection is unknown." (PMID 32365117, 2020). "Here we elucidated novel roles for S. Typhimurium chitinases (ChiA and STM0233) in promoting infection by enhancing small intestinal invasion." (PMID 35482787, 2022). "Deletion of ChiA resulted in only slightly reduced invasion of non-intestinal epithelial cells and no competitive advantage of wild type S. Typhimurium over ChiA-deficient S. Typhimurium in a mixed infection mouse model, questioning the relevance of S. Typhimurium chitinases for pathogenicity." (PMID 35482787, 2022). "Therefore, we compared the kinetics of Acp6.9-chiA/polh-cath infection of cultured cells to that of AcEGFP, AcMNPV-Rep, and Acp6.9-chiA to determine if CHIA and V-CATH enzyme levels were deleterious to the Acp6.9-chiA/polh-cath infection cycle." (PMID 36851718, 2023). "The native baculovirus chiA and v-cath genes are not conserved in all baculoviruses, and are each considered an auxiliary gene for per os infection and the cellular production of budded and occluded virions." (PMID 36851718, 2023). "Even though ChiA has demonstrated activity towards LacNAc residues, we did not detect broad removal of LacNAc residues during infection." (PMID 35482787, 2022). "We found a significant reduction in the surface MHC-II level with WT infection, but not in ΔchiA infection, indicating that Salmonella ChiA facilitates pathogen survival by dampening host antimicrobial responses." (PMID 35482710, 2022). "L. monocytogenes strains lacking ChiA showed decreased colonization of the spleen and liver during murine infection." (PMID 35482787, 2022). "The ability of ChiA to bind non-chitin substrates implies that during intracellular infection ChiA interacts with other specific host cytoplasmic glycoproteins and may modulate host pathways either through their requisitioning to the LCV or through their hydrolysis." (PMID 32365117, 2020).
tumor (5 papers, 2016 to 2025). "This analysis confirmed that the expression levels were significantly associated with the type of tissue (normal vs. tumor) for the eight fusion transcripts and also found a significant effect for a ninth, namely CHIA–PIFO (P = 0.0184)." (PMID 27058892, 2016). "Since the likely human homolog of Ym1 is acidic mammalian chitinase (gene name: CHIA), it would be interesting to determine the function of CHIA-positive TILs in tumor biology." (PMID 33322099, 2020). "Also of note, for some genes, more than one component is present (HTR4 E and S for STES/tumor status, CHIA E and S for LGG/tumor status, AFP E and S for LGG/tumor status)." (PMID 32625238, 2020).
bacterial infection (1 paper, 2020). "The four CHIA, CHI3L2, PRDM2 and KDM5B genes that we identified on BTA4 and 16 in the Swedish Red Cattle were previously reported as disease resistance genes (i.e. to gastrointestinal nematodes or bacterial infection) in independent studies on sheep and cattle breeds." (PMID 32887549, 2020).
CHIA also shares sentences with these, for which no sentence is quoted: eosinophilia (6 papers); pulmonary fibrosis (5); allergic asthma (3); Allergy (3); cancer (3); inflammation (3); airway hyperresponsiveness (2); ascariasis (2); cryptococcal infection (2); cyst (2); diabetes (2); dry eye syndrome (2); fungal infection (2); gastric cancer (2); hyperreactivity (2); aspergillosis (1); autism (1); cardiovascular diseases (1); chronic obstructive lung disease (1); corneal infection (1); eumycetoma (1); gastric adenocarcinoma (1); gastritis (1); Gaucher disease (1); Granuloma (1); helminth infections (1); idiopathic pulmonary fibrosis (1); liver cancer (1); lung disease (1); nematode infections (1).
A further 9 diseases each share a sentence with CHIA in 1 paper.